DCBLD2 (discoidin, CUB and LCCL domain containing 2)
Diseases named in the same sentence as DCBLD2 in open-access papers (continued):
Sharing a sentence is not in itself a finding about the gene and the disease.
tumor (continued). "The results showed that DCBLD2 and HTRA1 were highly expressed in tumor tissues, and DCBLD2 was mainly expressed in fibroblasts and myofibroblasts, HTRA1 was mainly upregulated in endothelial cells and fibroblasts." (PMID 39790460, 2025). "By the GEPIA platform, we conducted an expression analysis at the RNA level and discovered significant upregulation of SERPINB3, LY6D, DCBLD2, and ANLN within PC tumor tissues." (PMID 41427028, 2025). "The expression of CCL20, CD70, PCDH7, DCBLD2, and MMP14 genes were remarkably more elevated within LUAD samples than adjacent non-tumorous tissues, where PIK3R5, RNF144B, BTG2, CD69, and MEP1A genes were the opposite." (PMID 36497225, 2022). "KEGG pathway data suggested that DCBLD2 regulates the Rap1, PI3K-Akt, and Ras signalling pathways during tumor pathogenesis." (PMID 36034778, 2022). "The application of cisplatin further upregulates the expression of DCBLD2 via ERK/AP-1 axis and facilitates tumor metastasis." (PMID 33808696, 2021). "The IHC staining data showed that the jetPEI-delivered DCBLD2 siRNA efficiently inhibited DCBLD2 expression, which blocked EMT when mice were treated with cisplatin, leading to increased E-cadherin and decreased Vimentin expression in tumor tissues." (PMID 33808696, 2021). "To investigate the differential expression of DCBLD2 mRNA, we compared DCBLD2 mRNA expression in 57 LUAD specimens, including tumor tissues and paired normal tissues, from the TCGA database." (PMID 33808696, 2021). "We further identified the crucial role and the mechanism of DCBLD2 in cisplatin-induced EMT and tumor metastasis." (PMID 33808696, 2021). "We also observed that CD70, ITGB4, and DCBLD2 were significant prognostic indicators in crosstalk and cell-cell communication between LUAD tumor cells and T cells." (PMID 32549766, 2020). "We show that NT5E is a target of the TNF-α signaling in vitro; the tumor suppressor PPARγ acts as a novel NT5E antagonist that positively and concomitantly regulates DCBLD2 in a cancer cell context-dependent manner." (PMID 24133572, 2013). "In our tumor validation set we focused on AKAP12, DCBLD2, NT5E with a higher stringent threshold cut-off, and SPON1 whose expression appears to be highly cancer-related in the explorative “training series”." (PMID 24133572, 2013). "In some case high DCBLD2/ESDN expression coincided with very low levels of TFAP2A in tumor cells, while in other cases DCBLD2/ESDN high or low expression co-existed with high TFAP2A expression." (PMID 20525283, 2010). "Several genes thought to play a role in the processes of invasion, tumour progression and metastasis (MME, STAT3, DCBLD2, S100A10, CD9, S100A8) were highly downregulated in the NE vs the non-NE tumour group." (PMID 18827820, 2008). "Functional experiments have demonstrated that downregulation of DCBLD2 affects tumor cell migration, but not proliferation." (PMID 39790460, 2025). "Furthermore, we analyzed the protein expression levels of ANLN, DCBLD2, LY6D, and SERPINB3 using the UALCAN platform, which were notably upregulated within PC tumor tissues." (PMID 41427028, 2025). "Besides, F3, DCBLD2, and TNFAIP6 were detected at low level in both non-tumor cells and tumor cells." (PMID 36180938, 2022). "Secondly, we only performed bioinformatics analysis of DCBLD2 expression, tumor stage, and prognosis in different databases, rather than in vivo/in vitro experiments." (PMID 36034778, 2022). "DCBLD2 stabilizes β-catenin by phosphorylating GSK3β and transporting accumulated β-catenin to the nucleus to promote the expression of EMT-related transcriptional factors (TFs), ultimately resulting in tumor metastasis." (PMID 33808696, 2021). "DCBLD2 and GSDMD have considerable tumour-specific effects, but their roles in PDAC development remain unclear." (PMID 32958051, 2020).
tumor (continued). "AKAP12, DCBLD2, NT5E and SPON1 are particularly represented in the signatures and selected for validation in vivo on two independent patients cohorts comprising 140 tumor tissues and 60 matched normal tissues." (PMID 24133572, 2013). "Various functional studies link DCBLD2/ESDN to tumor progression but a specific role in tumor promotion or repression has not been defined yet." (PMID 20525283, 2010). "Thus, its interesting to note that several genes thought to play a role in the processes of invasion, tumour progression and metastasis (MME, STAT3, DCBLD2, S100A10, CD9, S100A8) were highly downregulated in the NE vs the non-NE tumour group." (PMID 18827820, 2008). "However in HeLa cells, used for our microarray analysis, we demonstrated that TFAP2A regulates tumor cell motility and invasion, at least partially, via DCBLD2/ESDN in a negative manner." (PMID 20525283, 2010). "The top differentially expressed transcripts between tumor and non-tumor were TPX2, DCBLD2 and ANLN which were significantly increased in tumors (T∶N ratio>2.0, P<0.01), and CDO1, DPEP1, C7, ALDH1A1 and NR3C2 which were significantly decreased in tumors (T∶N ratio<0.2, P<0.01)." (PMID 22363658, 2012).
cancer (20 papers, 2013 to 2025). A tumor composed of atypical neoplastic, often pleomorphic cells that invade other tissues. "Aberrant DCBLD2 expression strongly correlated with cancer-associated fibroblast infiltration and prognosis in multiple cancers." (PMID 38714870, 2024). "Nevertheless, further investigations are needed to elucidate the mechanisms underlying the effects of drugs on DCBLD2 expression and cancer progression." (PMID 38714870, 2024). "The strong correlation between abnormal DCBLD2 expression, cancer-associated fibroblast infiltration, and patient survival across various cancers underscores their significance." (PMID 38714870, 2024). "Although several research evidences at the cellular and clinical levels have associated DCBLD2 with tumorigenesis, nothing is known regarding this gene from a pan-cancer standpoint." (PMID 36034778, 2022). "At present, nothing is known regarding systematic regulation of DCBLD2 on tumorigenesis, prognosis, and drug susceptibility in pan-cancer, while knowledge on the relationship between DCBLD2 and TME, including immune infiltration, is still lacking." (PMID 36034778, 2022). "Spearman correlation of the 16 hypoxia genes and 151 chemo drugs in the Genomics of Drug Sensitivity in Cancer database revealed that the expression of DCBLD2, PLEC, S100A11, PLAT, PPAP2B and LAMC2 was associated with resistance to most chemotherapies." (PMID 35155430, 2022). "DCBLD2 has previously been associated with tumourigenic activity in several other cancer types, and accordingly the observed positive correlation between high DCBLD2 expression and increased MFS invasiveness was selected for further assessment." (PMID 31722230, 2020). "Additionally, we observed a significant correlation between aberrant DCBLD2 expression, the infiltration of immune cells (particularly cancer-associated fibroblasts), and overall survival in patients with various cancer types." (PMID 38714870, 2024). "Functional enrichment revealed that DCBLD2 might be involved in cell motility, angiogenesis, and cancer-associated pathways." (PMID 33834039, 2021). "Significantly, increased DCBLD2 expression was linked to poorer overall survival in 8 types of cancer, inferior disease-free survival in 3 types of cancer, inferior disease-specific survival in 7 types of cancer, and inferior progression-free survival in 7 types of cancer (Cox p < 0.05)." (PMID 38714870, 2024). "In most cases, DCBLD2 expression is moderately positive and strongly associated with the quantity of multiple infiltrating immune cells, such as neutrophils, cancer-associated fibroblasts (CAFs), endothelial cells, and myeloid-derived suppressor cells (MDSCs), in different types of cancer." (PMID 38714870, 2024). "Using TIMER 2.0, we conducted a comprehensive analysis across different types of cancer and discovered a strong positive correlation between DCBLD2 expression and the levels of infiltrating immune cells." (PMID 38714870, 2024). "Hypermethylation of the DCBLD2 gene promoter stimulated cancer cell proliferation and the invasion of SNU cell lineages." (PMID 36768307, 2023). "Reported literature has revealed that DCBLD2 influences the emergence and progression of multiple diseases, including cancer." (PMID 36034778, 2022). "Results revealed that DCBLD2 expression in cancer cells was positively correlated with IC50 values of many chemotherapeutic drugs, targeted drugs, and small molecular probes, including 5-Fluorouracil." (PMID 36034778, 2022). "Here, we provide the first report of the effects of DCBLD2 on tumorigenesis, prognosis, immune infiltration, and drug sensitivity in pan-cancer based on a dataset from TCGA." (PMID 36034778, 2022). "Our study extends the scope of those observations to demonstrate that in addition to regulating growth factor signaling in vascular and cancer cells, DCBLD2 modulates BMP2 expression and signaling in EC and VIC." (PMID 35540096, 2022).
cancer (continued). "Next, we utilized the GEPIA 2.0 tool to include gene expression data of all cancer samples and selected the top 100 genes that were related to DCBLD2 expression." (PMID 36034778, 2022). "In this study, we systematically analyzed the influence of DCBLD2 on prognosis, cancer staging, immune characteristics, and drug sensitivity in a variety of cancers based on a unified and standardized pan-cancer dataset." (PMID 36034778, 2022). "Our findings indicate that DCBLD2 is an oncogenic, immunological, and prognostic factor and has the potential to be a biomarker for cancer diagnosis, drug development, and prognostic analyses." (PMID 36034778, 2022). "In this view, we analyzed the relationship between DCBLD2 expression and cancer-related pathway activity at the pan-cancer level, revealing that DCBLD2 activated EMT signalling in 31 different types of tumors." (PMID 36034778, 2022). "In gastric cancer, DCBLD2 is downregulated by epigenetic modification, and it exhibits a suppressive role in cancer cell proliferation and invasion." (PMID 33834039, 2021). "The plasma membrane receptors DCBLD1 and DCBLD2 modulate basic cellular processes that are fundamental to vertebrate development, glucose homeostasis, and the progression of certain cancers." (PMID 32606017, 2020). "Approximately 60Kb telomeric and in sense orientation to ST3GAL6-AS1, is located the DCBLD2 (Discoidin, CUB and LCCL Domain Containing 2) gene encoding a receptor tyrosine kinase with aberrant expression in malignant tumors." (PMID 32218309, 2020). "The Discoidin, CUB, and LCCL domain-containing protein (DCBLD) family consists of two type-I transmembrane scaffolding receptors, DCBLD1 and DCBLD2, which play important roles in development and cancer." (PMID 32606017, 2020). "The reported up-regulated transcription of DCBLD2 in CRC is in agreement with up-regulated levels of the derived circ_0066631 in the cancer stem cells of CRC reported in this work." (PMID 33114016, 2020). "DCBLD2 has been reported to be involved in vasculature remodeling and insulin sensitivity, and is also up-regulated in a variety of cancers." (PMID 29025973, 2017). "Notably, the presence of CAFs is strongly correlated with the expression of DCBLD2 in various cancer types." (PMID 38714870, 2024). "Furthermore, notable associations were detected between aberrant DCBLD2 expression and CAF infiltration and overall survival in patients with various types of cancer." (PMID 38714870, 2024). "The findings demonstrated that DCBLD2 can promote the occurrence and deterioration of multiple tumors, and it has the potential to be a biomarker to predict the prognosis of patients from the perspective of pan-cancer." (PMID 36034778, 2022). "Therefore, our findings indicate that DCBLD2 is an oncogenic, immunological, and prognostic factor and has the potential to be a biomarker for cancer diagnosis, drug development, and prognostic analyses." (PMID 36034778, 2022). "For the first time, we performed a pan-cancer analysis of DCBLD2, and the results revealed a was a statistically significant association of DCBLD2 expression with pathological stage, prognosis, immune regulation, and chemotherapeutic and targeted drug sensitivity." (PMID 36034778, 2022). "This discovery could partly explain the protective effect of DCBLD2 in certain forms of cancer." (PMID 38714870, 2024). "Thus, our hypothesis is that targeting DCBLD2 could emerge as an optimal approach for the treatment of cancer patients." (PMID 38714870, 2024). "The remaining nine surface proteins identified solely (ANTXR1, AG1, DCBLD2, EFNB1, EMB, OSMR, SLC1A5) or found upregulated (ATP1B3 and ITGB1) on the MCF10A surface had no direct association with embryonic development signaling in the context of KRas mutant signaling in cancer cell lines." (PMID 27894102, 2016). "The eight mRNAs selected for further analysis, AXL, SCG5, VOPP1, DCBLD2 and DRAM1 are cancer-promoting genes, DUSP1, AQP5 and BLNK are cancer suppressor genes." (PMID 37925175, 2023).
cancer (continued). "The results revealed five cancer-promoting genes (AXL, SCG5, VOPP1, DCBLD2, DRAM1), and three tumor suppressor genes (DUSP1, AQP5, BLNK)." (PMID 37925175, 2023). "Mmu-miR-505-5p was downregulated in Sca-1+CD31− compared to Sca-1+CD31+ cells, with targets Cyp1b1, Dcbld2, Igf1, and Ppp1r14b,Txndc5 increased in expression; Igf1 was involved in mTOR and PI3K-Akt signaling and Cyp1b1by with microRNAs in cancer." (PMID 27298624, 2016). "In particular, we noted that DCBLD2 exhibited significantly greater expression in cancer vs. normal samples for 8 cancer types." (PMID 38714870, 2024). "Currently, no study has investigated whether DCBLD2 regulates the immune microenvironment and pathogenesis of tumors from the pan-cancer landscape." (PMID 36034778, 2022). "The roles of DCBLD2, E2F7, and KRT6A have not been explored in PDAC but these proteins are known to have context dependent effects in various cancers." (PMID 30092011, 2018).
DCBLD2 also shares sentences with these, for which no sentence is quoted: bladder cancer (2 papers); lung adenocarcinoma (2); neuroendocrine carcinoma (2); breast tumours (1); chronic pancreatitis (1); COVID-19 (1); infection (1); myopia (1); ovarian carcinoma (1); restrictive cardiomyopathy (1); thrombosis (1).